TNF (tumor necrosis factor)
Diseases named in the same sentence as TNF in open-access papers (continued):
Sharing a sentence is not in itself a finding about the gene and the disease.
Arthritis (continued). "Despite our observation that PAD4 is not critical for total lung citrullination in TNF+ mice, we hypothesized that PAD4 might be important for TNF-α-induced lung inflammation since it contributes to TNF-α-induced joint inflammation." (PMID 27450561, 2016). "Indeed, neutralizing antibodies to TNFα, one of the most important proinflammatory cytokine containing AREs, prevent arthritis in transgenic mice expressing ARE-lacking stable TNFα transcripts, which produce pathological overexpression of TNFα." (PMID 21776382, 2011). "Hence, despite the strong dependency of IL-17 on TNFα in a naive joint, IL-17 acts both synergistically with and independent of TNF and IL-1 under arthritis conditions." (PMID 20003323, 2009). "Arthritis develops due to the lack of immune regulation resulting from CTLA-4 and PD-1/PD-L1 suppression, leading to unchecked T-cell responses, elevation of IL-17 and TNF-α, and infiltration of effector memory CD8+ T-cells into the synovium, which differentiates it from autoantibody-mediated RA." (PMID 41239350, 2025). "Secreted by Th1 cells and macrophages, TNF-α was initially thought to play a synergistic role in the development of RA However, follow-up studies indicated that excessive activation of TNF-α signaling led to arthritis even in the absence of functional T and B cells." (PMID 39636801, 2024). "However, in the huTNFtg model of arthritis, this could not apply as the endogenous 3′UTR of the human TNF gene is replaced by the 3′UTR of the HBB gene." (PMID 39235454, 2024).
inflammatory bowel disease (1,527 papers, 2006 to 2026). A spectrum of small and large bowel inflammatory diseases of unknown etiology. "Differentiating inflammatory bowel disease (IBD) flares from infectious complications in patients on anti-TNFα therapy presents a significant diagnostic challenge." (PMID 41793591, 2026). "In humans, Mucispirillum species are linked to inflammatory bowel disease and Parkinson’s disease, particularly in those individuals with sub-inflammation and elevated TNF-α and IFN-γ levels." (PMID 40564914, 2025). "TNF-alpha inhibitors in combination with thiopurines have been associated with both B- and T-cell non-Hodgkin lymphomas when used in patients with inflammatory bowel disease (IBD)." (PMID 40893576, 2025). "Hypermethylation of the TNF-α gene promoter is associated with diminished expression of this cytokine, a key component of the inflammatory response in inflammatory bowel disease (IBD)." (PMID 41425918, 2025). "TNF-α overexpression can cause chronic inflammatory and autoimmune diseases, such as chronic inflammatory arthritis, inflammatory bowel disease (IBD), and multiple sclerosis (MS)." (PMID 40722600, 2025). "This study aims to identify the metabolites that can inhibit TNFα/NFκB signaling and are potentially therapeutic against various TNFα-associated inflammatory diseases, particularly inflammatory bowel diseases." (PMID 40605975, 2025). "Ruminococcus, associated with active inflammatory bowel disease, stimulates immune system cells, such as tumor necrosis factor-alpha (TNF-α), which mediates the differentiation of osteoclasts and osteoblasts, contributing to postmenopausal osteoporosis." (PMID 40270955, 2025). "This review provides a comprehensive synthesis of current evidence on the role of HLA genotypes in inflammatory bowel disease susceptibility and disease behavior, with a focus on their mechanistic and clinical relevance in anti-TNF therapy." (PMID 40806407, 2025). "For instance, anti-TNF therapy reduced the incidence of PD in patients with inflammatory bowel disease, and polymorphisms in the TNF gene have been associated with an increased risk for PD." (PMID 40111902, 2025). "IL17‐producing cells are concentrated in the intestinal mucosa and submucosa of patients with inflammatory bowel disease, and they are functionally linked with a pro‐inflammatory role via the upregulation of TNFα, IL1B, IL6, IL8, and neutrophil recruitment." (PMID 38992956, 2024). "For example, most models of TNF excess, either by transgenic overexpression or by deletion of the AU-rich instability element, are associated with a severe form of inflammatory bowel disease." (PMID 37903626, 2024). "This cohort study examines the association of incident use of tumor necrosis factor (TNF) inhibitors with subsequent decline in kidney function and risk of all-cause mortality among patients with new-onset inflammatory bowel disease (IBD)." (PMID 38625700, 2024). "Later, specific adverse events were described depending on the biological agent used: TNF-α inhibitors were linked to tuberculosis, while anti-IL-17 agents were associated with candidiasis and worsening of inflammatory bowel disease (IBD)." (PMID 39569269, 2024). "IL-2, IL-1β, IFN-γ, IL-6, TNF-α, and IL-8 is a pro-inflammatory cytokine associated with inflammatory bowel disease, and the pro-inflammatory cytokine response is a critical pathophysiological factor in the acceleration of the occurrence and development of UC." (PMID 39473926, 2024). "The genetic polymorphisms rs2395185 and rs2097432 in HLA genes have been associated with the response to anti-TNF treatment in inflammatory bowel disease (IBD)." (PMID 36675312, 2023). "Anti‐TNF therapy has shown an inverse association with the outcome of death or hospital admission in COVID‐19 patients with inflammatory bowel diseases." (PMID 37382255, 2023).
inflammatory bowel disease (continued). "Meanwhile, the KEGG results revealed the genes were enriched in the TNF signaling pathway, pathogenic Escherichia coli infection, inflammatory bowel disease and tight junction." (PMID 37016023, 2023). "Sleep disruption has been associated with increased levels of inflammatory cytokines, such as IL‐6, and TNF‐α, that have been implicated in the pathogenesis of inflammatory bowel disease." (PMID 36968569, 2023). "The studies of Xiao-Yu Ai confirm that apigenin effectively inhibits inflammatory bowel disease and colitis-associated cancer through decreased levels of the inflammatory cytokines TNF-α, IL-1β, IL-6, MCP-1, and CSF-1 and of COX-2 in tumors." (PMID 36836951, 2023). "Anti-TNFα drugs, Etanercept or Infliximab, were used in 10 patients with resolution of fever and associated symptoms, improvement of growth, inflammatory bowel disease and neurologic symptoms." (PMID 35984545, 2023). "In general, long-term elevated TNF-α levels are associated with conditions such as inflammatory bowel disease, and lowering the levels of this cytokine is generally considered to have a beneficial anti-inflammatory effect." (PMID 37630833, 2023). "A special case is SS associated with inflammatory bowel disease, where TNF-α inhibitors, including etanercept, infliximab, and adalimumab, have demonstrated efficacy." (PMID 37958609, 2023). "It is well-established that IL-1β and TNF-α are among the main pathogenic factors that contribute to damage in conditions such as Crohn’s disease and other inflammatory bowel diseases." (PMID 38249453, 2023). "Defects in the control of TNF expression are associated with several human pathologies, including rheumatoid arthritis and inflammatory bowel disease." (PMID 36973252, 2023). "Madcam1 has been linked previously to TNF-α and is an important player in the development of inflammatory bowel diseases, but only few studies describe Madcam1 in the context of retinopathies, in contrast to other adhesion molecules like Vcam1." (PMID 36371417, 2022). "The pro‐inflammatory cytokine TNFα is linked to pain in both patients with inflammatory bowel disease and irritable bowel syndrome, and has been shown to sensitize colonic sensory neurons." (PMID 35775903, 2022). "One tissue that does appear to be sensitive to proinflammatory mediators, such as TNFα, is the intestinal tract, and lymphatic dysfunction does appear to play a pathogenic role in mouse models of inflammatory bowel disease." (PMID 35927983, 2022). "Treatment of inflammatory bowel disease with TNF-alpha antagonists (n = 548) was associated with a shorter duration of the vaccine response." (PMID 36585405, 2022). "As a prevalent gut microbe, Ruminococcus gnavus is associated with Crohn's disease (a major type of inflammatory bowel disease), which potently induces inflammatory cytokine (TNF-α) secretion by dendritic cells." (PMID 36407546, 2022). "Infliximab is an anti-tumor necrosis factor-alpha (anti-TNF-α) monoclonal antibody, which is widely used for treating inflammatory bowel disease, and it is known to increase the risk of rare and opportunistic infections." (PMID 35070572, 2022). "PJP has also been described in association with the anti-tumor necrosis factor-α (TNFα) monoclonal antibody infliximab, which is broadly used in patients with autoimmune disease and inflammatory bowel disease." (PMID 36354934, 2022). "Dysregulation of TNF production has been implicated in a variety of human diseases including cancer and inflammatory bowel disease." (PMID 33800186, 2021). "Overexpression of pro-inflammatory IL-8, along ide IL-6 and TNF-α, has been associated with inflammatory processes in the digestive system, particularly in the intestines, inducing inflammatory bowel disease (IBD)." (PMID 34203479, 2021). "The loss of response to anti-TNF agents―and, consequently, DI―occurred frequently in inflammatory bowel disease (approximately in one-fourth at one year and in one-third at 3 years)." (PMID 34069295, 2021).
inflammatory bowel disease (continued). "A recent study has reported faster healing of periapical tissues when a TNFα antibody was used as an anti-inflammatory therapy in inflammatory bowel disease patients, who are considered to be at high risk of therapy-resistant AP12." (PMID 33510341, 2021). "Inflammatory bowel disease (IBD) is caused by excess tumor necrosis factor (TNF)-α in the lamina propria." (PMID 33805888, 2021). "TNF-α can cause mucosal inflammation and intestinal barrier injury and is a key factor in inducing inflammatory bowel disease." (PMID 34208038, 2021). "TNF-α is another mast cell mediator that has long been implicated in the pathogenesis of inflammatory bowel diseases such as ulcerative colitis and Crohn’s disease where TNF-α inhibitors such as infliximab have been mainstays of therapy." (PMID 34063789, 2021). "Disruption of TNFα production underlies numerous diseases, including inflammatory bowel disease (IBD) and cancer." (PMID 33406733, 2021). "This cohort study examines the association between use of anti–tumor necrosis factor (TNF) therapy or corticosteroids and all-cause mortality in a national cohort of veterans with inflammatory bowel disease (IBD)." (PMID 33646314, 2021). "Loss of response to antitumor necrosis factor (anti-TNF) therapies in inflammatory bowel disease occurs in a high proportion of patients." (PMID 34069295, 2021). "In some autoimmune diseases, namely, inflammatory bowel diseases and myasthenia gravis, there is an association between polymorphism and increased levels of TNF-α." (PMID 34778454, 2021). "There is one study in patients with inflammatory bowel disease that previously had cancer, where the authors found that anti-TNFα treatment had a mild risk of incident cancer." (PMID 32391269, 2020). "Vitamin D deficiency has also been associated with reduced efficacy of anti-TNFα treatment in inflammatory bowel diseases (IBD)." (PMID 33266022, 2020). "A recent paper also demonstrated that anti-TNF-α therapy in inflammatory bowel disease (IBD) induced a twofold increase in the risk of opportunistic infections." (PMID 29867964, 2018). "The expression of IL-34 increases with inflammation in patients with inflammatory bowel disease and experimental colitis and is associated with an elevated TNFα and IL-6 expression." (PMID 29472590, 2018). "The most common gene target studied has been the inflammatory cytokine, TNF-α, which is produced by macrophages and has been implicated in the progression of inflammatory bowel disease." (PMID 26192592, 2015). "The proinflammatory cytokines IL-1β and TNF-α, associated with inflammatory bowel diseases, exert different effects on gut epithelial cells monitored by the secretion of different combinations of chemokines in CEC." (PMID 25944986, 2015). "Clinically, many studies have implicated TNFα’s intricate link to intestinal barrier disruption in inflammatory bowel diseases such as Crohn’s disease and ulcerative colitis." (PMID 26589571, 2015). "Th17 cells are a subset of CD4+ T cells that can secrete IL-17, IL-22, IL-6, and TNF-α, and have been implicated in autoimmune diseases, including multiple sclerosis, lupus, inflammatory bowel disease, RA, IDDM, and experimental autoimmune encephalomyelitis." (PMID 24586733, 2014). "The SNP we identified in the current study has been associated with susceptibility to inflammatory bowel disease, as well as response to anti-TNF treatment, in a large Danish cohort." (PMID 25549360, 2014). "The TNF-α −308 G/A polymorphism was significantly associated with susceptibility to asthma in patients of South Iran and with susceptibility to inflammatory bowel disease in European population." (PMID 23284977, 2012). "NSAID use is associated with relapse of inflammatory bowel disease, further suggesting that up-regulation of TNF-α due to NSAID therapy is clinically relevant." (PMID 20027220, 2009).
inflammatory bowel disease (continued). "The importance of AREs in regulation of TNF-α production is evidenced by spontaneous development of chronic inflammatory arthritis and Crohn's-like inflammatory bowel disease in transgenic mice devoid of AREs in mRNA encoding TNF-α." (PMID 18796140, 2008). "Beyond its bone- resorptive effects, TNF-α also mediates systemic inflammation and has been implicated in the pathogenesis of various chronic diseases, including rheumatoid arthritis, inflammatory bowel disease, metabolic syndrome, and cardiovascular disease [10, -12]." (PMID 41466098, 2025). "TNF-α inhibitors not only improve inflammation-associated bone metabolic disorders but also show therapeutic potential in inflammatory bone loss diseases such as RA, inflammatory bowel disease (IBD), and ankylosing spondylitis (AS)." (PMID 40873591, 2025). "The increase in the abundance of norank_f__Erysipelotrichaceae has a causal relationship with a lower risk of inflammatory bowel disease, and it is negatively correlated with inflammatory factors such as TNF-α, while positively correlated with occludin and ZO-1." (PMID 40809052, 2025). "Similarly, the SNP C/T within the OCT1-binding site located in the promoter of TNF gene appears to alter constitutive TNF expression and is associated with the susceptibility to inflammatory bowel disease." (PMID 38254723, 2024). "MMP-9, IL-6, and TNF-α are pathogenic factors playing a crucial role in the progression of inflammatory responses in the gastrointestinal tract (for instance in patients with inflammatory bowel disease), causing an increase in intestinal permeability." (PMID 37997993, 2023). "In addition, TNF-α is a pro-inflammatory factor produced by macrophages, and plays an important pathogenic role in inflammatory bowel disease." (PMID 36902386, 2023). "TNFα and IL-6 in particular have been implicated in the association between chronic inflammatory conditions and growth, including environmental enteric dysfunction, inflammatory bowel disease, and juvenile arthritis." (PMID 36123771, 2022). "TNF-α and IL-1β are pleiotropic pro-inflammatory cytokines, whose dysregulations are linked with a wide range of pathological conditions, such as infection, metabolic syndrome and inflammatory bowel disease." (PMID 35436978, 2022). "In general, the long-term elevated levels of TNF-α associated with diseases such as arthritis, inflammatory bowel disease (IBD) or some specific types of cancer can be deleterious, and the reduction in the levels of this cytokine is generally considered a beneficial anti-inflammatory effect." (PMID 36010524, 2022). "However, because of this broad spectrum of cellular effects, TNF-α is also implicated in various disease states, such as inflammatory bowel diseases, infectious diseases, intestinal wound healing and tumor formation." (PMID 35939430, 2022). "PWV could also be potentially used to assess the efficacy of anti-TNF-alpha immunotherapy on arterial wall stiffness, and thus predict the risk of developing cardiovascular manifestations in patients with inflammatory bowel disease." (PMID 34123641, 2021). "However, it was reported in the literature that rs2275913 was associated with response to anti-TNF therapy among patients with inflammatory bowel disease." (PMID 34744511, 2021). "On the basis of its participation in chronic inflammatory disease, TNFα is believed to be implicated in several carcinogenetic processes, including colorectal cancer in patients with inflammatory bowel diseases and cholangiocarcinoma in patients with primary sclerosing cholangitis." (PMID 30764482, 2019). "SNPs in LD (R2=0.91) with rs7137828 include rs3184504 (48% frequency, p=4×10−8), a missense variant in the SH2B3 gene, associated with blood pressure, maternal birth weight, TNF-α levels, colorectal cancer, Inflammatory Bowel Disease, LDL cholesterol levels and stroke." (PMID 29227965, 2017).